MERTK (MER proto-oncogene, tyrosine kinase)
Diseases named in the same sentence as MERTK in open-access papers (continued):
Sharing a sentence is not in itself a finding about the gene and the disease.
tumor (continued). "Both MERTK and AXL are expressed in a wide variety of human cancers, including NSCLC, melanoma, leukemia, breast, colon, liver, gastric, prostate, ovarian, and brain cancers, where they promote tumor cell survival and/or proliferation and contribute to oncogenesis." (PMID 34830794, 2021). "Macrophage-specific MerTK is also a therapeutic target of interest, with improved survival rates seen with inhibitory mAbs combined with RT-anti-PD1 in lung adenocarcinomas, and tumour regression when combined with RT and TGFβ blockade in poorly immunogenic tumour models." (PMID 33148287, 2020). "Therefore, inhibition of MERTK and IDO1 produces an anti-tumor effect, which benefits the host." (PMID 32346605, 2020). "Only 1 patient did not express MerTK in the cells of the tumor microenvironment." (PMID 32363092, 2020). "MerTK expression was absent in breasts from healthy patients or in normal tissue adjacent to tumor." (PMID 33101282, 2020). "Therefore, TMAs were categorised to have either high or low MERTK expression (more or < 5% cytoplasm/membrane‐positive tumour cells) without distinguishing between these compartments." (PMID 29101300, 2017). "Thus, while treatment with MRX-2843 combined with venetoclax or navitoclax provided robust anti-tumor activity in the studies reported here, the combined inhibition of BCL-XL, MCL1 and MERTK may provide even further improvement in therapeutic efficacy against EWS." (PMID 39199601, 2024). "In addition, MerTK signaling promotes the secretion of anti-inflammatory cytokines, such as transforming growth factor-β (TGFβ), hepatocyte growth factor (HGF), and IL-10, resulting in immunosuppressive, pro-tumor, M2-polarized macrophages in the tumor microenvironment (TME)." (PMID 38443968, 2024). "Moreover, dendritic cells are known to preferentially utilize Axl for efferocytosis, with current MERTK inhibitors showing good selectivity for MERTK over the other TAM receptors, indicating that TAM-dependent uptake of tumor antigens by dendritic cells may be minimally affected by MERTK inhibition." (PMID 34065321, 2021). "SAV1 appears to be an important component for MERTK-inhibition triggered Akt inactivation, and the SAV1 expression status could be one marker of whether MERTK inhibitors, which are entering clinical trials, will be efficacious as anti-tumor cell-directed therapies." (PMID 30944303, 2019). "MerTK‐KO and negative control MKN45 cells were injected subcutaneously into athymic nude mice, and tumor volumes were measured every other day." (PMID 38545840, 2024). "This abscopal, anti-tumor effect was lacking in mice treated with XRT+αPD1, suggesting that the MerTK ASO was able to convert αPD1-resistant tumors to αPD1-sensitive tumors." (PMID 38443968, 2024). "Elevated MERTK expression in both tumor cells and macrophages contributes to TKI resistance by promoting cell polarity and stemness in tumor cells while sending 'do not eat me’ signals that help maintain an immunosuppressive TME." (PMID 39286635, 2024). "The co-culture of live LN-229 with parental HMC3, SIRPα-negative and MERTK-negative cells yielded low % GFP+ CD40+ cells (~5%), indicating low activities of tumor phagocytosis." (PMID 37483607, 2023). "PROS1 and GAS6 are produced by tumor cells and nonneoplastic cells in TME, which function as bridging molecules that are the physical link between MerTK and Phosphatidylserine (PtdSer)." (PMID 36497444, 2022). "Quantitative RT-PCR analysis of 8 tumor xenograft-derived cell lines showed that none had lost expression of either GAS6 or AXL; in fact, 6 of 8 had acquired significantly increased expression of MERTK (also activated by Gas6) and KDR." (PMID 34292953, 2021). "Although persistent AXL/GAS6 co-overexpression and acquired MERTK and KDR overexpression did not accelerate tumor xenograft growth rate, other concurrent phenotypic changes might nonetheless bear on disease progression." (PMID 34292953, 2021).
cancer (113 papers, 2013 to 2026). A tumor composed of atypical neoplastic, often pleomorphic cells that invade other tissues. "BACKGROUND: Myeloid epithelial reproductive tyrosine kinase (MERTK) receptor is overexpressed in cancers and is associated with poor prognosis." (PMID 41896977, 2026). "Mechanism and effect of quercetin on different cell lines and cancers within MerTK‐associated signaling pathways." (PMID 41195524, 2025). "MerTK is implicated in a wide variety of diseases including cancer, cardiovascular disease and brain pathologies." (PMID 38341954, 2024). "On the cancer cell, MerTK expression is associated with lower levels of apoptosis, increased proliferation, and cell cycle dysregulation." (PMID 38791148, 2024). "Our big data analytics show that MerTK is extensively expressed in cardiovascular diseases, brain disorders and cancer, which account for the major causes of death worldwide." (PMID 38341954, 2024). "Preclinical studies using murine cancer models have implicated MERTK and TAM RTKs in general as promising immunotherapeutic targets in multiple solid cancers." (PMID 39062902, 2024). "MERTK, which was found specifically in the group with T2D, also exhibited a unique association with cancer mortality and demonstrated a significant interaction effect with T2D when examined in the total study group." (PMID 39334377, 2024). "AXL is a member of the TAM (TYRO3, AXL, and MERTK) receptor tyrosine kinases family (RTKs), and its abnormal expression has been linked to clinicopathological features and poor prognosis of cancer patients." (PMID 37328828, 2023). "MerTK is shown to be overexpressed in cancer cells and is commonly linked to cell survival, proliferation, metastasis, chemoresistance, and PDL1 expression." (PMID 38035101, 2023). "Loss of MERTK is proposed to hinder macrophage-dependent phagocytosis of dead or dying cancer cells (efferocytosis)." (PMID 35969037, 2022). "The TAM subfamily (Tyro3, Axl, MerTK) of receptor tyrosine kinases are implicated in several cancers, where they have been shown to support primary tumorigenesis as well as secondary resistance to cancer therapies." (PMID 31766614, 2019). "The MER proto-oncogene, tyrosine kinase (MERTK), which is associated with cancer progression, was overexpressed 9-fold in PC-9/NaqR cells relative to the parental cells." (PMID 29386539, 2018). "The TAM family of proto-oncogenic receptor protein tyrosine kinases, comprising of TYRO3, AXL, and MERTK, is implicated in many human cancers." (PMID 28118606, 2017). "Furthermore, since its discovery MERTK has been linked to the pathogenesis of cancer in which MERTK has been observed to be overly or ectopically expressed." (PMID 38783191, 2024). "High MerTK expression was associated with the high three scores in 3–5 types of cancers." (PMID 36059952, 2022). "Importantly, numerous studies in various cancer diseases have been able to show that expression of MerTK is associated with a worse outcome." (PMID 33801886, 2021). "The oncogenic and cancer-promoting mechanisms of MerTK are associated with the classic cell proliferation pathways phosphatidylinositol 3 kinase (PI3K)/protein-serine-threonine kinase (Akt) and mitogen-activated protein kinase (MAPK)/extracellular signal-regulated kinase (ERK)." (PMID 32370748, 2020). "The TAM (Tyro3, Axl, MerTK) subfamily of receptor tyrosine kinases (RTKs) and their ligands, Gas6 and protein S (ProS1), are implicated in tumorigenesis and chemoresistance in various cancers." (PMID 32664510, 2020). "In addition to the regulation of PD-L1 expression in cancer cells, the expression of PD-L1 in monocytes and macrophages was downregulated in MERTK-deficient mice or in MERTK-wild-type mice which were treated with an MERTK inhibitor called MRX-2843." (PMID 33562150, 2021). "Gene groups linked to efferocytosis, including Tyro3, Axl, MerTK, Gas6, BAI-1, CX3CL1, CD31, CD47, Rac1, and the TIM family, represent significant targets for prospective cancer therapies." (PMID 39911848, 2025).
cancer (continued). "Axl, a member of the receptor tyrosine kinase family comprised of Tyro3, Axl, and MerTK, is a promising cancer therapeutic target actively under clinical investigation." (PMID 40539073, 2025). "The purpose of this review is to review quercetin's potential as a new supplemental treatment for cancer, with a focus on the myeloid‐epithelial‐reproductive tyrosine kinase (MerTK) pathway and the downstream signaling cascades." (PMID 41195524, 2025). "Advanced delivery systems and combination strategies with MerTK inhibitors can overcome its clinical limitations and enhance its efficacy in cancer therapies." (PMID 41195524, 2025). "ONO-7475, a dual inhibitor targeting AXL and MERTK, has shown potential in combination therapies for overcoming resistance in various cancers." (PMID 39924521, 2025). "Our previous study revealed that cancer-secreted Hsp70 exerts a marked immunosuppressive effect in TME mediated through MerTK and TLR2." (PMID 40227806, 2025). "Due to the structural similarity of the TAM receptor family, usage of MerTK inhibitors in anti‐cancer approaches can result in elevated off‐target effects and toxicity." (PMID 41195524, 2025). "Dysregulation of MERTK has been observed in various types of cancers, implicating its involvement in tumorigenesis and cancer progression." (PMID 41166341, 2025). "In order to target cancer cells and get around the drawbacks of monotherapies, combination treatments employing quercetin and MerTK inhibitors provide a synergistic strategy." (PMID 41195524, 2025). "Our results revealed that cancer cell-secreted Hsp70 induces MerTK upregulation and promotes polarization of immunosuppressive M2 macrophages." (PMID 40227806, 2025). "MerTK and Axl have become promising targets for cancer immunotherapy, particularly in tumors with a high burden of myeloid-driven immune suppression." (PMID 40821795, 2025). "Examples for MerTK inhibitors: introducing potential MerTK‐targeting compounds for cancer therapies." (PMID 41195524, 2025). "In relation to a potential role in the TME, we recently published a study revealing that Hsp70, secreted by PDAC cancer cells, promotes M2 MΦ polarization through the induction of Mer receptor tyrosine kinase (MerTK) upregulation." (PMID 40227806, 2025). "MRX-2843 (UNC2371)−, is a MerTK inhibitor and immune modulator currently undergoing Phase1 clinical trials for cancer therapy." (PMID 40391976, 2025). "The existing challenges in utilizing MerTK inhibitors in cancer therapies motivated us to investigate the possibilities of using quercetin as a complementary factor." (PMID 41195524, 2025). "In patient studies, elevated expression of MerTK and Axl in TAMs or circulating monocytes has been correlated with poor prognosis, advanced disease stage, and resistance to immunotherapy in cancers." (PMID 40821795, 2025). "MERTK, which has been identified for its oncogenic characteristics, is commonly overexpressed or activated in many cancers." (PMID 41166341, 2025). "Laboratory research and clinical trials are required to validate the prospects of combination therapies with quercetin and MerTK inhibitors on cancer patients." (PMID 41195524, 2025). "These dynamic insights into the PROS1-MERTK complex, highlighted by significant structural adaptability and the presence of specific binding interfaces, offer promising therapeutic avenues for cancers where MERTK signaling is deregulated." (PMID 39535659, 2025). "The number of studies describing the role of MerTK in cancer progression and development, as well as its role in therapeutic strategies, has increased significantly." (PMID 41226428, 2025). "The identified dysregulations in various cancers highlight MERTK as a potential target for novel therapeutic interventions." (PMID 41166341, 2025). "We have also dissected the role of MERTK in immune system physiology and pathology and provided insight into the interplay of MERTK in cancer and immune microenvironment." (PMID 39062902, 2024).
cancer (continued). "To rule out that reduced efferocytosis activity in KO macrophages was due to a defect in the recognition of phosphatidylserine on apoptotic cancer cells by TAMs, we measured mRNA levels of receptor tyrosine kinase family members such as MerTK, Tyro3, and Axl." (PMID 38308188, 2024). "Compared to normal conditions, MerTK expression in related tissues is altered in many human diseases, including cardiovascular diseases, cancer, and brain disorders." (PMID 38341954, 2024). "A variety of other structurally distinct MERTK inhibitors with potent activity in cancer are also available." (PMID 39062902, 2024). "These pathways contribute to MERTK’s cancer-promoting properties, such as its capacity to transform NIH 3T3 fibroblasts and to render Ba/F3 cells independent of IL-3 for survival and growth." (PMID 39062902, 2024). "Other investigators have also reported that the overexpression of MerTK promotes cancer cell migration." (PMID 38791148, 2024). "The inhibition of MerTK induces the accumulation of cancer apoptotic cells and triggers a type I interferon response." (PMID 38891056, 2024). "MerTK also is considered a potentially novel therapeutic target for the treatment of cancer since it can regulate the innate immune response, tissue homeostasis and repair, and platelet aggregation." (PMID 38341954, 2024). "Although aberrant MerTK expression has been found in many cancers, the mechanisms of increased cell proliferation and invasion driven by MerTK signaling in TNBC is still unclear." (PMID 38791148, 2024). "We have evidence that some cancer models are amenable to improvements in anti-tumor immunity when Mertk is ablated, and thus, the role of MERTK in anti-tumor immunity is context-specific." (PMID 38791338, 2024). "MERTK is a receptor tyrosine kinase aberrantly expressed in several malignancies and represents a novel target for cancer therapeutics." (PMID 38703764, 2024). "MERTK has been identified as having a pathological role in cancer due to its ectopic and aberrant expression across a wide spectrum of human cancers." (PMID 39062902, 2024). "Potential targets for cancer therapy include efferocytosis-related genes and pathways, such as phosphatidylserine, TYRO3, MerTK, indoleamine-2,3-dioxygenase 1, membrane-linked protein V, CD 47, TGF-β, and IL-10." (PMID 37853449, 2023). "Another intriguing target is merTK (myeloid-epithelial-reproductive tyrosine kinase), a tyrosine kinase receptor found in various cancers as well as TAMs." (PMID 38035101, 2023). "As we used immunocompromised NSG mice in our cancer models, an immune-related effect leading to increased bone volume by MERTK blockade is unlikely." (PMID 36509738, 2022). "Studies are underway to develop small-molecule chemicals that inhibit MERTK as cancer immunotherapeutic agents, but these efforts are in their early stages." (PMID 36056187, 2022). "Myeloid epithelial reproductive proto-oncogene tyrosine kinase (MERTK) plays an essential role in modulating cancer immune tolerance by regulating macrophage efferocytosis." (PMID 36056187, 2022). "MerTK (Mer tyrosine kinase), a receptor tyrosine kinase, is ectopically or aberrantly expressed in numerous human hematologic and solid malignancies." (PMID 35268561, 2022). "MERTK signalling pathway inhibition reduced cancer cell viability and induced cytokine expression in the immune-suppressive M2 macrophages." (PMID 35626092, 2022). "Upon AXL inhibition, MERTK is upregulated in several cancer models and constitutes one of many mechanisms of drug resistance build-up." (PMID 35626092, 2022). "It is firmly established that MERTK inhibition on cancer cells inhibits survival signaling pathways." (PMID 33801886, 2021). "Next to being overexpressed in many cancers, MERTK and FLT3 have important roles in immune cell development and function." (PMID 34835225, 2021).
cancer (continued). "In this regard, CD206 and MERTK expression were found within the immune infiltrate in multiple solid tumors, highlighting its potential role in cancer immunity." (PMID 34065977, 2021). "As a consequence, cancer cells express all the prerequisites to MerTK autosignaling, which has been demonstrated to assist in formation of metastases, chemoresistance and proliferation." (PMID 33801886, 2021). "The upregulation of MERTK can be observed in recurrent tumors of cancer patients who received target therapy or chemotherapy as their first-line treatment." (PMID 33562150, 2021). "It has been shown that MERTK is involved in the phenotypic and genotypic alterations of cancer cells and microenvironmental regulation." (PMID 33562150, 2021). "Due to apoptotic mimicry, cancer cells seduce macrophages to silent phagocytosis via MerTK signaling instead of triggering an inflammatory response." (PMID 33801886, 2021). "While most aspects of Tyro3 are understudied, data are accumulating concerning the complex biology of MerTK and Axl in cells, tissues, the immune system and cancer." (PMID 33801886, 2021). "The receptor tyrosine kinases Tyro3, Axl and MerTK—belonging to the TAM family—exert a large impact on various aspects of cancer biology." (PMID 34771611, 2021). "Recently, evidence has showed that MERTK can function as a pro-angiogenic gene and promotes the metastasis of human cancers." (PMID 33562150, 2021). "MerTK activation initiates a signaling cascade in cancer cells that classically promotes cancer cell survival, and in T cells provides a costimulatory signal." (PMID 33801886, 2021). "TAM receptors also play important roles in cancer biology, which has prompted investigations on inhibition of mainly Axl and MerTK as a therapeutic strategy." (PMID 33801886, 2021). "Further study is required to fully interrogate the duality between beneficial and detrimental effects of MerTK and Axl inhibition in cancer treatment and its consequences for the immune system." (PMID 33801886, 2021). "We discuss the current standing and future prospects of MerTK and Axl inhibition in the treatment of cancer and the balancing act that must be maintained to limit any potential detrimental effects on immune cells." (PMID 33801886, 2021). "Clinical trials are ongoing to investigate the therapeutic potential of Axl and MerTK small molecule inhibitors in cancer and data from these trials will provide valuable insights into the precise mechanism of action." (PMID 33801886, 2021). "A wide range of cancers have been demonstrated to express high levels of MerTK, in both blood malignancies and solid cancers, resulting in gathering interest in the targeting of MerTK for cancer treatment." (PMID 33801886, 2021). "Although using a TMA does not allow us to perform quantitative or clinical evaluation of MerTK in situ, it provides an interesting overview of MerTK frequent expression in various cancers, supporting its potential as a target for cancer therapy." (PMID 33101282, 2020). "Aberrant expression of MerTK was reported to promote the cell survival, invasive motility, and chemoresistance of a number of human cancers." (PMID 33114206, 2020). "Aberrant tyrosine-protein kinase Mer (MerTK) expression triggers prosurvival signaling and contributes to cell survival, invasive motility, and chemoresistance in many kinds of cancers." (PMID 33114206, 2020). "We identified MerTK expression in multiple cancer tissues, expressed either by cancers cells or by mononuclear cells in the stroma." (PMID 33101282, 2020). "Collectively, this underscores the pitfalls of MERTK-inhibitors as cancer treatment, specifically in combination with T cell-based immunotherapy." (PMID 31664482, 2020). "It had been reported previously that MerTK- or PROS1-deficient mice display lower levels of IL-10 production by myeloid cells following bacterial or viral activation, or in cancer models." (PMID 33101282, 2020).